BAX (BCL2 associated X, apoptosis regulator)
Diseases named in the same sentence as BAX in open-access papers (continued):
Sharing a sentence is not in itself a finding about the gene and the disease.
tumor (continued). "However, active effectors (BAX and BAK) or initiator (PMAIP1, BIK and BID) cannot lead to apoptosis in tumours, and these pro‐apoptotic proteins may be sequestered by guardians (BCL2 and BCL2L1) that have more potent enhancer activity to propel the anti‐apoptotic mechanisms." (PMID 32419250, 2020). "In the multivariate Cox regression analysis, BAX mRNA expression predicted a significantly favorable prognostic outcome (HR = 0.33, 95% CI = 0.13–0.84, P = 0.020), independent of patients’ gender, age, tumor histology, tumor extent, and regional lymph node status." (PMID 23777485, 2013). "Interestingly, overall bulk tumor response to 17-AAG is independent of BAX status, both in vitro and in vivo, which is likely due to the predominance of a cytostatic antiproliferative response combined with the induction of an alternative cell death mechanism when apoptosis is blocked." (PMID 24185264, 2013). "The lack of significant differences in VEGF, BAX, and BCL2 expression indicates that dynamic culture conditions preserve the tumor phenotype while providing a more controlled and “biomimetic” in vitro environment." (PMID 41439917, 2025). "In conclusion, there was no change in BAX or Bcl-2 gene and protein expression in response to ECT at the time points evaluated, but ECT was able to reduce tumor volume and cellular proliferation in cSCC." (PMID 31676831, 2019). "Pro-apoptotic factors such as BAX, BAK, and Bad and the anti-apoptotic factors Bcl2 and Bcl-xl are delicately balanced, and this balance is often lacking in tumor cells." (PMID 30686270, 2019). "An approximate 4-fold induction of cells staining positive for caspase-3 cleavage was observed in HCT116 BAX+/− tumor xenografts, which was absent in isogenic HCT116 BAX−/− tumor xenografts." (PMID 24185264, 2013). "In accordance with these findings, Cox regression analysis revealed that BAX mRNA expression can be considered as a favorable prognostic indicator of DFS and OS in NPC, independent of their gender, age, tumor histology, tumor extent, and nodal status." (PMID 23777485, 2013). "Increased expression of two pro-apoptotic genes, BAX and BAK, were detected following treatment of pxn100 tumours, but not pxn65 tumours." (PMID 15452549, 2004). "Those patients who simultaneously expressed BAX and BCL-2 had a longer progression-free and overall survival compared to patients whose tumours did not express BCL-2 (P = 0.05 and 0.015 respectively)." (PMID 11720475, 2001). "Inactivation of the BAX/BAK apoptotic pathway is essential for tumor growth, and cells that express functional BAK and BAX could not survive under hypoxic conditions." (PMID 33996599, 2021). "However, the BAX gene did not significantly increase in the CUR-treated cells, and BAX/BCL2 ratio was significantly increased in B16-F10 tumor cells (P < 0.0001)." (PMID 34825002, 2021). "Besides, there were no significant changes in Bcl-2, BAX and Caspase-3 expression in tumor tissue from LNPS@Scrambled Bcl-2 treated tumor-bearing mice as compared with what were from normal saline treated tumor-bearing mice." (PMID 28514759, 2017).
tumor (continued). "Moreover, because we concurrently assessed clinical, pathologic and tumor molecular variables such as the CpG island methylator phenotype (CIMP), LINE-1 methylation, KRAS, BRAF and PIK3CA mutations, we could evaluate the effect of TGFBR2 or BAX mutation independent of these potential confounders." (PMID 21949851, 2011). "Our results suggest that BAX status may not alter clinical response to HSP90 inhibitors and indicate that additional drugs may be required in combination to increase tumor-selective cell killing by these clinically promising drugs, such as combination with TRAIL or HSP70 inhibitors." (PMID 24185264, 2013).
infection (74 papers, 2009 to 2026). The state of being infected such as from the introduction of a foreign agent such as serum, vaccine, antigenic substance or organism. "Treatment with BCLXL inhibitors, as well as deficient BCLXL gene expression, induced BAX/BAK-dependent apoptosis upon infection with flaviviruses." (PMID 30261081, 2018). "In support of these observations, injection of the WT BcCcp1-His6, but not the H131L mutant, into Nicotiana benthamiana leaves reduced H2O2 accumulation and cell death caused by BAX and, as a result, enhanced the infection of Phytophthora capsici, a biotrophic plant pathogen." (PMID 35932761, 2022). "We also observed the release of cytochrome C from mitochondria and the aggregation of the apoptosis regulator BCL2-associated X (BAX) on the mitochondrial outer membrane 48 h post-infection, indicating that the intrinsic apoptotic pathway played a critical role in ZIKV-induced cell death." (PMID 33424801, 2020). "Avr1b and Avh331 from P. sojae inhibit cell death induced by the pro-apoptotic protein BAX and contribute positively to virulence, indicating that suppression of immunity-associated cell death by effectors is a feasible strategy for pathogen infection." (PMID 31105658, 2019). "Mechanistically, we observed time-dependent upregulation of TGF-β1 and its downstream effector GADD45b during infection, with subsequent induction of the pro-apoptotic factor BAX." (PMID 40879372, 2025). "To further characterize the temporal dynamics of apoptosis during infection, we examined expression of BAX, a pro-apoptotic factor regulated by GADD45b." (PMID 40879372, 2025). "Given that BAX-mediated apoptosis typically requires an induction window of ~18–24 hours, its upregulation during mid-infection likely facilitates virus release through apoptosis during late stages." (PMID 40879372, 2025). "Studies have shown that LPS infection enhanced the expression of Caspase-3, Caspase-8, Caspase-9, and BAX genes and proteins while reducing the levels of BCL-2 gene expression and protein abundance." (PMID 40136393, 2025). "CVS inhibits apoptosis by downregulating the expression of pro-apoptotic gene BAX in the early stages of infection, but triggers apoptosis in the later stages of infection by increasing the release of cytochrome c and upregulating the expression of AIF." (PMID 38247875, 2024). "The activation of BAK/BAX has been demonstrated to be responsible for mtDNA release under SFTSV infection." (PMID 38712963, 2024). "USP30 is regulated by post-translational modifications and takes an active part in many cellular events such as infection, autophagy, BAX/ bak-dependent apoptosis, and tumorigenesis." (PMID 38364250, 2024). "The levels of BAX mRNA in the infection group gradually increased compared with those of the control group while those of Bcl-xL mRNA trended downward." (PMID 37175500, 2023). "In both in vitro and in vivo experiments, rNDV or rNDV‐TRAIL infection activated BAX production and deactivated Bcl‐2 production, particularly evident in the BAX/Bcl‐2 ratio, which exhibited a more substantial increase in HT‐29 cells compared to HCT116 cells." (PMID 37843231, 2023). "The finding was that at 12 hours after infection, the expression of Bcl-2 and BAX was similar, but there was an increase in the expression of PARP in infected cells." (PMID 37186587, 2023). "Due to the significance of suppression of defense-related HR in plant cells during infection, BAX/INF1-triggered programmed cell death (BT-PCD/IT-PCD) was employed as an imitation of HR to examine the effector activity against plant immunity." (PMID 36439212, 2022).
infection (continued). "Both HCMV and MCMV also suppress mitochondrial cell death by targeting the B cell lymphoma-2 (BCL2)-associated X protein (BAX) and BCL-2 homologous antagonistic killer (BAK) during infection." (PMID 34578288, 2021). "Recently, it has been demonstrated that HCMV vMIA suppresses BAX/BAK-dependent signaling to facilitate the infection of mast cells." (PMID 34578288, 2021). "TNFR1 plays a role early in infection, but BAX/BAK activity bypasses any contribution from this cytokine later in infection." (PMID 34578288, 2021). "A liver-derived cell line that is amenable for infection by AAV8 was needed to analyze the biological function of BAX 335 in vitro." (PMID 32280725, 2020). "We also found that FYC and its main components inhibited the expression of BAX induced by infection and increased the expression of Bcl-2." (PMID 31312226, 2019). "Meanwhile, the expression of innate immune-related genes TNF-α, CCL3, and BAX was upregulated both by infection and fenofibrate at an early stage of incubation (4 h), with higher expression levels with the merge of infection and fenofibrate than by the two conditions separately." (PMID 38543516, 2024). "Interestingly, BI-1, which encodes for an anti-apoptotic protein that indirectly inhibits the pro-apoptotic factor BAX, was transcriptionally induced under infection with L. fungicola." (PMID 38279283, 2024). "Additionally, Chlamydia induces caspase-independent apoptosis due to the overexpression of BAX at the end of infection cycle to mediate release of Chlamydia." (PMID 36453900, 2022). "The expression of BAX apoptotic gene increased after infection of MSCs with reovirus." (PMID 33933086, 2021). "It is possible that in the context of infection, BAX and BAK may contribute to cell death by inducing LMP instead of MOMP." (PMID 32897321, 2021). "Here, we used the Nicotiana benthamiana transient expression system to show that a virulence-associated effector, CCG_07874, from C. chrysosperma is induced upon infection and functions in the early stage of infection to suppress the PCD caused by Bcl-2-associated X protein (BAX) and INF1." (PMID 33627507, 2021). "For instance, both pathways may lead to activation of BAX and BAX-dependent caspase-independent modes of cell death were proposed to play a role in Chlamydia exit at the late stage of infection." (PMID 30375511, 2019). "Although no increase of infectious particle production was observed in BAX/BAKDKO cells until 2-days post-infection, three to ten times of increase of infectious titer compared to parental Huh7 cells was observed in BAX/BAKDKO cells at 3 and 4 days post-infection." (PMID 30261081, 2018). "We next determined whether ABT-737 treatment induces BAX/BAK-dependent cell death upon infection with flaviviruses." (PMID 30261081, 2018). "The Ad-HRD1 infection significantly suppressed BAX and restored Bcl-2 expression." (PMID 29233968, 2017). "This could explain the BIM/BAX reduction in the late stage of the infection." (PMID 38644830, 2024). "However, further work is needed to delineate how BAX/BAK activation is regulated during infection and whether these signals can fine‐tune cell death and inflammatory responses in diverse innate immune cells." (PMID 37846472, 2023). "In this study, we found that bladder samples form patients with SCI were characterized by protein expressions patterns indicative of accelerated cell apoptosis (increased BAX) and cell proliferation (increased Ki-67), which may indicate the attempt to respond to and defend against infection." (PMID 35203430, 2022).
infection (continued). "Thus, during the course of infection, macrophages may support necroptosis with reduced inflammatory markers, extrinsic apoptosis with elevated inflammatory markers, and activated BAX/BAK-dependent signaling with reduced inflammatory markers." (PMID 34578288, 2021). "WB analysis showed that following ME49 infection, AZD1208-treated mice exhibited significantly reduced BCL-2 protein levels and significantly elevated BAX and cleaved-Caspase3 protein levels compared to the control and Pyrimethamine groups." (PMID 41557744, 2026). "It is noteworthy, though, that the anti‐apoptotic (BCL2)/pro‐apoptotic (BAX) ratio significantly decreased only in SARS‐CoV‐2‐infected HCOs, indicating that after infection, apoptosis is somewhat enhanced in this neural model." (PMID 39950320, 2025). "In ciliated cells, the pro-apoptotic gene BAX and the executioner caspase CASP3 showed a time-dependent increase in expression following infection." (PMID 39735182, 2024). "Moreover, our recent study with a high multiplicity of infection (MOI) of Beijing-1 infection remarkably induced neuronal cell death via inducing the proteolysis of endogenous p21 BAX to generate more apoptogenic molecules of p18 BAX during the late stage of JEV infection." (PMID 37946006, 2024). "To determine the specific mechanism, we examined the levels of apoptosis-related genes (BAX, APAF-1, TNF-α, Caspase-9, Caspase-3, and BCL-2) in EBL cells following infection with M. bovis." (PMID 39308873, 2024). "We also observed increased M.tb growth in BAX/BAK KO relative to control BMDMs, similar to what has been reported in vivo in mice, likely due to baseline levels of apoptosis during infection that moderately limit M.tb growth." (PMID 37864894, 2023). "Our data support a role for A1 (and MCL‐1) in limiting NOMV‐induced BAX/BAK‐mediated apoptosis, necroptosis, and possibly pyroptosis in infiltrating inflammatory monocytes that act as bystander cells during extracellular infections." (PMID 37846472, 2023). "As expected, our findings revealed upregulated mRNA levels of the pro-apoptotic genes: BAX, COX-2, caspase-3, and iNOS induced by VRSA denoting infection and promoting apoptosis." (PMID 38282617, 2023). "Our data showed that H37Rv infection increased the BCL-2 transcript and protein, decreased the BAX transcript, and increased phosphorylated BCL-2 at the protein level." (PMID 35631013, 2022). "During infection, vMIA/vIBO suppress an early involvement of TNF beyond BAX/BAK such that the double-mutant virus drives TNFR1-dependent death by 24 hpi." (PMID 34578288, 2021). "All pro- (Casp-8, FADD, BAX, and BAK) or anti-apoptotic (BCL-2 and XIAP) genes tested were down regulated at early time points post-SVA infection (2–4 h p.i.)(p < 0.05 when compared to mock-infected cells)." (PMID 30918505, 2019). "Collectively, these results suggest that cell death is induced upon infection with JEV and treatment with ABT-737 through a BAX/BAK-dependent pathway." (PMID 30261081, 2018). "Infection with ΔflaA L. pneumophila resulted in the death of similar numbers of BAK−/− and BAX−/−BAK−/− BMDMs by 72 h post infection." (PMID 28261564, 2017).